IL10 (interleukin 10)
Diseases named in the same sentence as IL10 in open-access papers (continued):
Sharing a sentence is not in itself a finding about the gene and the disease.
cancer (continued). "A systematic literature search was conducted using the electronic databases ‘PubMed’, ‘Scopus’, and ‘Web of Science’ in December 2024 to identify relevant studies on IL-10 immunotherapy and cancer." (PMID 40149345, 2025). "We next focused on IL-10, a major anti-inflammatory cytokine with therapeutic potential in cancer and autoimmune disorders such as inflammatory bowel disease." (PMID 41279521, 2025). "Continued research and technological innovation are imperative to unlock the full therapeutic potential of IL-10, paving the way for more effective and durable cancer immunotherapies across diverse malignancies." (PMID 40149345, 2025). "Cancer cells significantly contribute to an immune-suppressive, pro-tumoral environment, particularly through the secretion of cytokines like IL-10, TGF-β, and colony-stimulating factor-1 (CSF-1)." (PMID 40002754, 2025). "IL-33-activated Tregs produce higher levels of cytokines, TGF-β and IL-10, which promote chronic inflammation and early cancer development while inhibiting the recruitment of antitumor cytotoxic CD8+ T cells." (PMID 40579434, 2025). "Several studies have demonstrated that IL-10 inhibits inflammatory immune signaling by downregulating pro-inflammatory cytokine expression, thereby acting as an antitumoral cytokine in certain cancers." (PMID 41153842, 2025). "In cancer, IL-10’s dual role is being intensively studied, particularly its potential to enhance antitumor responses with immune checkpoint inhibitors." (PMID 41376630, 2025). "Specifically, we engineer TGF-β-gated IL-2 (TGF-β→IL-2) and IL-10-gated IL-2 (IL-10→IL-2) cytokine adaptors that reverse T cell inhibition and have potential applications in cancer therapy." (PMID 40069219, 2025). "In HCC patients, B cells produce high levels of IL-10 and express PD-L1, contributing to the anti-cancer immune response." (PMID 40136652, 2025). "qRT-PCR analysis of these Tregs revealed that BST2 knockdown in the cancer cells led to a significant downregulation of the key Treg functional markers Foxp3 and IL-10." (PMID 41281378, 2025). "In conclusion, IL-10 represents a compelling avenue in cancer immunotherapy, with the potential to reshape treatment paradigms." (PMID 40149345, 2025). "Pegylated proteins, fusion proteins, nanoparticles, vector delivery systems, and genetically modified IL-10 are revolutionizing cancer research landscape." (PMID 40149345, 2025). "PD-L1 and IL-10 can work together, often in feedback loops, to repress immune responses in tumors: IL-10 promotes PD-L1 expression on cancer cells, and PD-L1 signaling also leads to IL-10 release." (PMID 41516315, 2025). "Regions of elevated tumor NOS2/COX2 would be expected to increase cancer cell stemness, thus leading to therapy resistance while causing increased activation of TGF-β and IL-10." (PMID 40663402, 2025). "The secretion of anti-inflammatory cytokines, such as IL-6, IL-10, and IL-13, can promote cancer stemness and contribute to the development of therapeutic resistance." (PMID 40800581, 2025). "NKG2D downregulation in cancer patients is mediated by cytokines such as TGFβ and IL‐10, as well as immunosuppressive molecules like prostaglandin E2 (PGE2), vascular endothelial growth factor (VEGF), nitric oxide synthase (NOS), and reactive oxygen species." (PMID 40389988, 2025). "Since the identification of the IL-10 family, researchers have been working to design IL-10-based therapeutic approaches for a range of conditions, including autoimmune disorders, infections, tissue damage and cancer." (PMID 41312367, 2025). "This work establishes a foundation for using IL-10 as a building block in cancer immunotherapy, improving its anti-inflammatory and anti-tumorigenic properties potential." (PMID 40149345, 2025). "In cancer, there is a growing recognition of C5aR as an immune checkpoint receptor, and C5aR deletion enhanced T‐cell antitumor activity via IL‐10." (PMID 41189475, 2025).
cancer (continued). "This abundance strictly correlates with the elevated levels of IL-6 and IL-10, advanced cancer stages and poor survival of patients." (PMID 40136652, 2025). "Within this framework, pegilodecakin (AM0010) has been the most extensively studied PEGylated IL-10 formulation in clinical cancer therapy." (PMID 40149345, 2025). "For instance, a longitudinal study illustrated that increased sleep duration or decreased SD were associated with the attenuation of pro-inflammatory biomarkers (such as IL-1β and IL-6) and the counter-regulatory cytokine (IL-10) among cancer survivors." (PMID 41470834, 2025). "Immunosuppressive cytokines TGF‐β and IL‐10 were also markedly increased in cancer tissues, with Fold Changes of 3.0 and 2.8, respectively (p < 0.01)." (PMID 40596746, 2025). "Pan-cancer analysis identified the abnormal upregulation of immune suppressive factors IL-10 and TGF-β1 across various cancers, highlighting their potential as universal therapeutic targets." (PMID 41438510, 2025). "As IL‐10 represents a central immunosuppressive mediator in the TME of various cancers, we examined its role in our 3D model." (PMID 41368078, 2025). "Mechanistically, NPD1 or ARU binding to GPR37 in macrophages promotes the release of IL-10, which further inhibits cancer-induced osteoclastogenesis." (PMID 39965073, 2025). "Th1 cells producing IFN-γ exhibit anti-cancer properties, while Th2 cells generating IL-10 and IL-4 support the humoral immune-response." (PMID 40403026, 2025). "Although multiple ICK strategies have been devised to stimulate antitumor immune responses, we herein focused on the most significant ICKs that specifically explore IL-10-based therapies in the preclinical cancer setting." (PMID 40149345, 2025). "Given the critical role of the IL-10 pathway in immune evasion, there is significant interest in developing strategies to modulate this pathway in cancer therapy." (PMID 40739089, 2025). "In contrast to previously discussed cytokines, IL-10 has traditionally been viewed as an anti-inflammatory cytokine, leading to the presumption that it attenuates the immune response against cancer." (PMID 39411143, 2024). "The cellular origins of IL-10 in MA are diverse, encompassing neutrophils, MDSCs, DCs, TAMs, T cells, B cells, and even cancer cells." (PMID 38279997, 2024). "Nevertheless, the exploration of IL-10 in cancer immunotherapy remains a topic of clinical interest, urging further investigation into potential combination strategies or IL-10 modifications." (PMID 39034318, 2024). "In contrast, the angiostatic cytokine profiles of TNFα, MIG, M-CSF, IL-10, and IFNγ in the host serum revealed a dramatic and significant decrease after day 5 post-implantation of cancer cells." (PMID 39451257, 2024). "On the other hand, treatment of cancer patients with daily subcutaneous PEGylated IL-10 resulted in immune and CD8+ T cell activation and serum IL-10 levels of 18.9 ng/mL, which is very similar to the perfusate IL-10 levels in our high-dose MSCIL-10 group." (PMID 38786082, 2024). "Future studies should test the clinical potential of targeting IL-10 and its downstream molecules in the context of PCa and investigate the pleiotropic effects of IL-10 in different cancers." (PMID 39202777, 2024). "Cancer patients, in comparison with healthy people and those with benign tumors, exhibit elevated levels of IL-10 in both serum and ascites, with this correlating with advanced clinical staging and poor outcomes." (PMID 38279997, 2024). "Regarding metabolic and cardiovascular biomarkers and cancer treatment, there were positive correlations between IL-6 and length of steroid therapy, and between IL-10 and cisplatin and ifosfamide total doses." (PMID 38254811, 2024). "Our findings indicated a significant relationship between LOXL2 expression and the majority of the genes in immune checkpoint pathways, like VEGFA, CD276, TGFB1, and IL10 in pan-cancer." (PMID 38922489, 2024).
cancer (continued). "Immunoregulatory functions of IL-10 have implications for cancer immunology and the pathogenesis of neuroinflammation and neurological disorders." (PMID 38248028, 2024). "Since IL-10 can be expressed by several cell types, including cancer cells, the origin as well as the exact functioning of IL-10 in the context of ICI treatment requires further investigation." (PMID 38355607, 2024). "Monocytes release various pro-inflammatory cytokines, including interleukins IL-1, IL-6, IL-10, and TNF-α, which are linked to reduced survival and a worse prognosis in patients with malignant tumors." (PMID 39493767, 2024). "Despite the varying perspectives, it's clear IL-10's impact on cancer is multifaceted, emphasizing the need for context-specific evaluations in understanding its role in oncogenesis and treatment." (PMID 39132165, 2024). "TIM4+ omental macrophages promoted cancer stem cell-like property acquisition and epithalami–mesenchymal transition in ovarian cancer and abundantly expressed IL-10 and TGF-β." (PMID 38303024, 2024). "IL-10 inhibition during vaccination has previously been shown to successfully improve the efficacy of DC-based cancer therapeutic vaccines." (PMID 38973612, 2024). "Studies have shown increased concentrations of multiple cytokines, including interleukin 6, TNFα, interleukin 8, the cytokines MIF, TGFβ, interleukin 10 and interleukin 18 in patients with cancer." (PMID 39020272, 2024). "We reviewed the levels, origins, and functions of IL-10 in malignant ascites and overviewed the current IL-10 signaling targeting therapies, aiming to provide insights for MA treatment." (PMID 38279997, 2024). "IL-10 has been shown in OC to possess immunosuppressive properties, namely the impairment of antigen presentation, the promotion of cancer stemness with M2 polarization of macrophages and the Th2 cell response." (PMID 39199610, 2024). "Immunosuppressive cytokines, such as TGFβ and IL-10, are secreted by cancer cells and stromal cells." (PMID 39125732, 2024). "The presence of DCs together with B cells strongly up-regulated IL-10 release, suggesting that DCs control Breg expansion in the presence of cancer cells and that IL-1β plays a key role in reducing IL-10 release." (PMID 39576827, 2024). "We investigated the expression levels of immunosuppressive markers, including PD-L1 and IL-10, in the PBMCs (macrophages and dendritic cells) and cancer mucosa of GC patients." (PMID 38197259, 2024). "The levels of IL-10 in MA exhibit considerable variability across different cancer types and even among patients with the same cancer type." (PMID 38279997, 2024). "It has been demonstrated that significantly elevated levels of IL-6, IL-8, and IL-10 are exhibited in cancers." (PMID 38337827, 2024). "In contrast, the anti-angiostatic MIG, M-CSF, IL-10, and IFNγ cytokines in the host serum revealed a dramatic and significant decrease after day 5 post-implantation of cancer cells." (PMID 39451257, 2024). "In brief LAG-3 is able to enhance regulatory T-lymphocytes levels through IL-10, resulting in a significant increase of cancer cells immune escape; therefore LAG-3 it is considered a new target of great clinical interest in cancer immunotherapy." (PMID 38322766, 2024). "In BC, hypoxia mediates neutral lipid accumulation in lung mesenchymal cells (MCs) via interleukin-10 (IL-10), and lipid-laden MCs transport lipids to cancer cells as well as NK cells via EVs, leading to BC lung metastasis and NK cell dysfunction." (PMID 39434182, 2024). "IL-10 plays a nuanced role in cancer, functioning as a critical regulator between homeostatic immunity and inflammation." (PMID 38672104, 2024). "We observed similar correlations in CESC, GBM, HNSC, and STAD cancers, where a strong association between CD59 and TAM is linked to worse prognosis through IL10/STAT3-dependent pathways." (PMID 39518137, 2024).
cancer (continued). "TGF-β has been detected in a wide range of cancers, alone or in combination with other immunosuppressive cytokines, such as IL-10, PGE2 and TNF-α." (PMID 39020402, 2024). "The results showed that IL10 silence alleviated the effects of MEIS2 on mobility and proliferation rate of BC cells, indicating that MEIS2 mediated the proliferation rate and mobility of cancer cells through IL10." (PMID 38711262, 2024). "M-E4BP4 showed increased expression of anti-inflammatory genes such as Retnla, IL10, and C1qa, and Ccl5, which is involved in immune escape of cancer, and decreased expression of pro-inflammatory genes such as Txnrd1, Odc1, Mmp1232,36–40." (PMID 38714733, 2024). "Although associations have been identified between IL-4, IL-6, IL-8, IL-10, IL-1β, TNF-α, COMT, CLOCK, PER, and 5-HTTLPR-related genes and cancer-related fatigue, the relationship between IL-6 and cancer-related fatigue remains controversial." (PMID 39372868, 2024). "GrB is a pro-apoptotic molecule constitutively expressed in human pDCs, but its production and release is further induced by cytokines, such as IL-3, IL-10 and IL-21, abundantly expressed in cancer tissues." (PMID 39020402, 2024). "Chemokines CCL7, CCL24, and CXCL13, as well as IL-10 and Bmp2, exert pro-tumorigenic effects in a variety of cancers, promoting the invasiveness, metastasis, and stemness of cancer cells." (PMID 38892209, 2024). "IL-10 is a multifunctional immunosuppressive cytokine secreted by Th2 cells, cancer cells and other cells and is an important cytokine that downregulates the activity of other immune cells and leads to persistent infection." (PMID 38693593, 2024). "The role of Il-10 in cancer pathogenesis and development is complex; Il-10 also plays an important role as an anti-inflammatory marker, inhibiting the synthesis of proinflammatory cytokines such as Il-6." (PMID 39202525, 2024). "IL-10’s role in cancer is complex, evidenced by its contribution to both immune suppression and stimulation within the FAP+ stromal compartments of diverse tumors such as NSCLC, PDAC, CRC, and RCC." (PMID 39035007, 2024). "IL-10 is a pleiotropic cytokine exerting both immunosuppression and immunostimulatory effects within the cancer microenvironment." (PMID 38279997, 2024). "IL‐10 is secreted by multiple cells, especially M2 TAMs, and regulates cell growth, differentiation, inflammatory and immune responses, and promote cancer progression." (PMID 38506082, 2024). "Research suggests that Treg’s ability to suppress cancer development triggered by microbial stimuli heavily relies on IL-10, which can downregulate pro-inflammatory cytokines like IL-6, thereby directly inhibiting Th2 cell activation." (PMID 39000453, 2024). "It is well known that in cancer patients, higher levels of IL-10 in serum correlate inversely with oncologic prognosis." (PMID 39199571, 2024). "IL10 is known as an anti‐inflammatory cytokine and can induce immunosuppression to help cancer cells to escape from immune surveillance." (PMID 38711262, 2024). "The level of IL-10 in MA varied across cancer types and patients, influencing cancer progression and outcomes." (PMID 38279997, 2024). "The F8 antibody carrying IL-10 is clinically being tested for the treatment of rheumatoid arthritis or ulcerative colitis and would be an interesting construct to assess for cancer therapy." (PMID 39204319, 2024). "Intercalarily, with these biotic applications, a decline in the values of IL-1, IFN-γ, TNF-α, and neopterin and a rise in the values of IL-10/-12/-13 were observed in cancer cells." (PMID 39045970, 2024). "The dominance of the Th2 subset is also evident by the enriched levels of type-2 cytokines, including IL4 and IL10, in the coculture of cancer and immune cells." (PMID 39544930, 2024). "This review focuses on ICKs designed with the most impactful cytokines in the cancer field: IL-2, TNFα, IL-10, IL-12, IL-15, IL-21, IFNγ, GM-CSF, and IFNα." (PMID 39204319, 2024).
cancer (continued). "The antitumor activity of interleukin-24 (IL-24), a unique cytokine cancer suppressor gene in the IL-10 cytokine family, has been demonstrated in a variety of tumors." (PMID 38711526, 2024). "Originating from various immune and cancer cells, IL-10 contributes to complex signaling pathways in MA." (PMID 38279997, 2024). "IL-10 exhibits a complex, dual role in antitumor immunity, with its effects shaped by various factors, including cancer type, cell type, TME conditions, and IL-10 concentration." (PMID 39726592, 2024). "Therefore, the paradox underlying the IL-10 blockade and whether it carries a beneficial or detrimental role in cancer treatment might be deciphered if we understood how exactly these cells react to IL-10 signalling through comprehensive genomic, epigenomic, and proteomic analysis." (PMID 38186186, 2024). "Out of these six members, IL-10 has been recognized as a major member mediating different functions within the immune system and cancer cells (Ref." (PMID 38186186, 2024). "The most prominent cytokines in our series, common to all cancers, are IL-6 and its soluble receptor IL-6Rα, TGFβ, IL-10, and G-CSF." (PMID 39114667, 2024). "As a cytokine, IL-10 mediates intercellular signaling that can influence immune and inflammatory responses, making its modulation a promising avenue for cancer immunotherapy." (PMID 38672104, 2024). "Several IL‐10R inhibitors have been reported that can block the binding of IL‐10 and IL‐10R, and potentially inhibit TAMs and cancer progression." (PMID 38506082, 2024). "While some studies have shown that IL-10 inhibits tumorigenesis, others have shown a correlation between high levels of IL-10 and an increased propensity for cancer cell survival and immune evasion." (PMID 38314029, 2024). "In a contradictory fashion, the cell subtype Th2 CD4+ instead promotes tumorgenicity and encourages metastasis by releasing cytokines IL-4, IL-5, and IL-13, but it also releases IL-10, which can influence either the growth or destruction of cancer cells." (PMID 39050852, 2024). "Serum concentrations of IL-10 were lower in cancer patients compared to healthy subjects and were also reduced in MIBC patients." (PMID 39684475, 2024). "In contrast, myoCAF-associated adipocytes, and the cancer-promoting microenvironment polarized macrophages towards an M2 phenotype, characterized by high CD163 receptor expression and IL-10 and TGF-β secretion." (PMID 39072314, 2024). "Our findings so far show that three of the peptides SPEA agonists have similar profiles of the full superantigen SPEA in activating the T- cells and producing different types of cytokines with an anti-cancer effect such as IL-1, IL-6, and IL-10." (PMID 37445686, 2023). "Although the infusion of IL-10 has been identified as a potential strategy for cancer immunotherapy, its long-term therapeutic efficacy has been hampered partially because it is rapidly cleared from the circulatory system." (PMID 37483629, 2023). "Previous studies showed that IFNβ has a growth inhibitory effect on cancer cells, upregulates the percentage of CD11blow macrophages, promotes the expression of IL-10, and reduces the expression of IL-12." (PMID 37445941, 2023). "In ccRCC, cancer-cell-derived factors such as IL-1β, IL-6, IL-10, tumor necrosis factor-α, epidermal growth factor, and TGF-β induce macrophage polarization towards a M2 phenotype by cell-cell interactions." (PMID 37842234, 2023). "IL-10 is overexpressed in patients with a variety of cancers, and elevated IL-10 expression is correlated with worse outcomes in cancer patients." (PMID 38102207, 2023). "IL-10 as an immune modulator can decrease detrimental inflammation, inhibit cancer progression, and curbing disease conditions." (PMID 37359549, 2023). "IL-10 has been indicated to suppress macrophage functions, leading to cancer cells’ evasion of host clearance." (PMID 38102207, 2023).